CTLA4 (cytotoxic T-lymphocyte associated protein 4)
Diseases named in the same sentence as CTLA4 in open-access papers (continued):
Sharing a sentence is not in itself a finding about the gene and the disease.
tumor (continued). "Since CTLA-4 expression is dynamically regulated in the TME, these results suggest that tumors with low CTLA4 mRNA expression may have fewer CTLA-4-positive cells (activated T, Treg, and tumor cells) or a lower amount of CTLA4 expression per cell." (PMID 37197667, 2023). "We observed tumor growth inhibition with anti–PD-1 treatment, but not anti-CTLA-4, and enhanced tumor growth inhibition with combination blockade." (PMID 37449205, 2023). "Noticeably, several immune checkpoints were significantly overexpressed in the S-AOIs as compared to E-AOIs, such as the T-cell-specific inhibitory receptor HAVCR2 and its corresponding tumor ligand LGALS9, or the inhibitory CD86 that interacts with CTLA4 on T-cells." (PMID 37460925, 2023). "The local expression of the anti-CTLA4 antibody resulted in significantly higher concentrations within the tumor, while plasma levels remained at nontoxic concentrations." (PMID 36768997, 2023). "Because CTLA-4 functions in the early stage of the T cell response in lymph nodes during tumor immunoregulation, it is possible for uncontrolled proliferation to occur in the absence of CTLA-4." (PMID 37895012, 2023). "One study found that CTLA-4 antibodies induced tumor rejection by selective depletion of regulatory T cells (Tregs) in the TME rather than blocking B7-CTLA-4 interaction in the lymphoid organs." (PMID 37251931, 2023). "Responsive tumour models used in this research, such as fibrosarcoma Sa1/N, 51BLim10, and RENCA, are relatively immunogenic and could be eradicated following the CTLA-4 blockade therapy." (PMID 37454231, 2023). "The combined anti-PD-1 and anti-CTLA-4 antibodies group and the combined oral administration of B. longum 420 with anti-PD-1 and anti-CTLA-4 antibodies group both showed significantly suppressed tumor growth compared to the PBS group at day 21 (p < 0.05)." (PMID 37340017, 2023). "The analyses indicated that cancer types with high KYNU gene expression (>median) generally had elevated gene-based signatures of tumor immune cell infiltrates, including Tregs, as well as immune checkpoint blockade-related genes CD274 (PD-L1), PDCD1 (PD-1), and CTLA4." (PMID 36765792, 2023). "With the application of ICBs, scientists have gradually realized that the immune activation generated by targeting CTLA-4 or PD-1 is not sufficient to control tumour progression." (PMID 37635168, 2023). "On the other hand, the cases without CTLA4+ cells in lymph nodes were 1.5 times more common in the IFN-γ-negative tumor group (χ2 = 3.6; p = 0.059)." (PMID 36979688, 2023). "When MWA is combined with anti-CTLA-4/PD-1 therapy, an increase in the CD8+ T-cell population may facilitate the clearance of unablated tumor cells, thereby protecting the host from tumor recurrence or neoplastic cells." (PMID 38139799, 2023). "A combination of DCsEVs and ICBs (anti-CTLA-4 therapy or PD-1/PD-L1 blockade) may further enhance the cross-priming of CD8+ T cells and alleviate the suppression of tumor-infiltrating CTLs." (PMID 37681880, 2023). "Hypoxic tissues secrete various chemokines to upregulate the expression of CTLA4 or LAG3 on Treg cells, as well as the PD-L1 ligand of MDSCs, TAMs and tumor cells, thus blocking the entry of antitumor T cells into the tumor core and promoting the recruitment of immunosuppressive cells." (PMID 38115906, 2023). "In various tumor types, increased expression of the T‐cell costimulatory molecule (ICOS) on PBLs and TILs has been observed after CTLA4 blockade, suggesting that ICOS on immune cells may serve as a potential biomarker for anti‐CTLA‐4 therapy." (PMID 38045830, 2023). "This was confirmed using anti-CTLA-4 + PDT combinations to increase survival of mice bearing CT26 tumours, and to regress lung metastases observed with bioluminescence in mice with orthotopic 4T1 tumours." (PMID 37468749, 2023).
tumor (continued). "These seminal studies on the balance between Teffs and Tregs suggest that increased numbers of tumour-infiltrating Teffs, rather than depletion of Tregs, can be used to predict sensitivity to anti-CTLA-4 immunotherapy." (PMID 37637050, 2023). "For instance, by binding to CTLA-4 on Tregs, ATOR-1015 can selectively deplete or down-regulate these cells, which are known to play a role in suppressing immune responses and promoting tumor growth." (PMID 37441075, 2023). "CTLA4 is constitutively expressed in Foxp3+ Tregs and CTLA-4-specific antagonistic antibodies not only augment effector T-cell activation but also induce ADCC-mediated depletion of tumor-infiltrating Tregs." (PMID 37928556, 2023). "In this study, we were not able to see correlations between CTLA4 DNA methylation and protein expression in the heterogeneous tumor sample." (PMID 37415208, 2023). "Nonetheless, the biopsy is limited to a small part of the tumor and cannot fully represent the CTLA4 level in the entire tumor, and surgery is not suitable for advanced ccRCC." (PMID 36397666, 2023). "Biomarker studies of anti‐CTLA4 therapies focused on the diversity of peripheral blood lymphocytes (PBLs) rather than tumor cells." (PMID 38045830, 2023). "But in PCa, many patients do not respond to monoclonal antibody therapy targeting PD1 or CTLA-4, possibly because tumor cells achieve immune escape through other pathways." (PMID 38203661, 2023). "Indeed, one possible mechanism for anti-CTLA4 antibody therapy is the depletion of immunosuppressive TGF-β-producing Treg cells, thereby promoting the costimulation and amplification of tumor-specific CTLs." (PMID 37649123, 2023). "Similar to anti-CTLA-4, anti-PD-L1 as a monotreatment induced a tumor growth delay without inducing cures, but resulted in CR in 50% of animals when combined with AU-011." (PMID 36997666, 2023). "Indeed, when PD-1 and CTLA-4 inhibitors were combined, we noted a modest therapeutic benefit in CT2A-luc tumor-bearing mice." (PMID 38213329, 2023). "Analysis of treated tumors demonstrates that targeting of a Toll-like receptor 7 agonist inhibits Treg expression of FOXP3, PD-1, CTLA4, and HELIOS, resulting in 40-80% reduction in tumor growth and repolarization of other tumor-infiltrating immune cells to more inflammatory phenotypes." (PMID 37928524, 2023). "Clinical trial results illustrated that anti-CTLA4 mAbs lead to acute immune activation, which increases CD8+ CTL infiltrates in the tumor and may produce transient autoimmune manifestations." (PMID 37568193, 2023). "When comparing CTLA-4 expression in different HNSCC cases, we observed a potential gradient of expression in adjacent epithelium (increasing from basal to superficial epidermal layer) and in tumors (increasing from periphery to center of the tumor)." (PMID 37415208, 2023). "In particular, several presentations outlined the effects of VISTA blockade, including a decrease in myeloid suppression of immune responses coupled with proinflammatory changes in the tumor microenvironment (TME) by mechanisms separate and distinct from PD-1 and CTLA-4 inhibition." (PMID 37795437, 2023). "We therefore list some possible target molecules (CD25, CD103, CD73, CCR4, CTLA-4, GITR, and Gr1) for NIR-PIT that induce knockdown of immune suppressor cells, especially Tregs, in the tumor microenvironment in order to activate anti-tumor responses." (PMID 36839882, 2023). "Meanwhile, the emergence of RUNX1 mutation, upregulations of genes expression (RPS27A, RPS6, UBA52, RACK1) on tumor cells, and increased frequencies of T and NK cells with TIGIT, CTLA4, and LAG3 expression were observed after midostaurin treatment, predicting the disease progression of this patient." (PMID 37638009, 2023). "Furthermore, it is reported that the expressions of CTLA4, PD‐1, LAG‐3, and PD‐L1 were correlated with immunosuppression of the tumor microenvironment." (PMID 37277111, 2023).
tumor (continued). "Given the unique role of immune checkpoint molecules in tumor immune microenvironment (TIME), we explored the expression of PD-1, PD-L1, LAG3, GAL9 and CTLA4 and found that the expression of these molecules was significantly elevated in pyrocluster A than that in pyrocluster B." (PMID 37221570, 2023). "Although anti–CTLA-4 alone inhibited tumor growth to a greater extent than mice treated with an isotype control (P = 0.0004), blockade of IL-6 alone did not delay tumor growth." (PMID 36881480, 2023). "In particular, we distinguish the tumor-specific immune abilities of CD8+ T, NK cells, and CD4+ T cells and describe the destructive ability of cytokine on tumor cells as well as the inhibitory capacity of CTLA-4 on various components." (PMID 36766849, 2023). "Some Mabs target EGFR, HER2, IGF‐1R, HGF, and VEGF; others may be checkpoint inhibitors (including Mabs to PD‐1, CTLA4, and NKG2A) or tumor‐targeting Mabs such as U36 and Mab E48." (PMID 37042307, 2023). "CTLA-4 and PDCD1 blockade could induce tumor immunity by improving effector T cell activity or consuming Treg." (PMID 36900015, 2023). "Delayed CD8+ T cell intratumoral infiltration was spatiotemporally aligned with cancer cell features of ferroptosis; this effect was enhanced by CTLA-4 blockade and recapitulated in vitro when tumor-draining lymph node CD8+ T cells were co-cultured with tumor cells." (PMID 36756111, 2023). "Although anti-Ly6C/CTLA-4 treatment achieved a significantly better outcome in terms of tumor growth and immune infiltration than that of anti-Ly6C/PD-1, dual blockade of Ly6C/CTLA-4 did not produce a curative effect." (PMID 37449205, 2023). "These checkpoint inhibitors could block the binding of PD-1 to PD-L1, PD-L2, or CTLA-4 to CD80/CD86, alleviating suppression of the immune response, including the tumor immune response." (PMID 37809090, 2023). "In mice with larger tumors that were poorly responsive to CpG + OX40, the addition of anti-CTLA-4 enhanced the anti-tumor efficacy in the A20 but not B78 models." (PMID 37016127, 2023). "The last mechanism is tumor cells generating adaptive immune resistance by secreting immunosuppressive cytokines (TGF-, VEGF), thereby inducing activation of Tregs and MDSCs and inhibiting immunosuppressive receptors (CTLA-4, PD-1, and Tim-3)." (PMID 36900322, 2023). "In mice bearing ~ 100 mm3 B78 tumors, the addition of anti-CTLA-4 causes a decrease in Tregs and an increase in T cell activation; even so, the addition of anti-CTLA-4 failed to improve the anti-tumor response of CpG + OX40." (PMID 37016127, 2023). "For example, cytotoxic T lymphocyte antigen-4 (CTLA-4) is an immune checkpoint molecule predominantly expressed on T-cells, and CTLA-4 blockade combined with radiotherapy significantly modulates the TCR repertoire of tumor-infiltrating T-cells." (PMID 38067199, 2023). "Immune checkpoint blockade can reinforce antitumor immunity by hindering intrinsic suppressors (e.g. CTLA4, PD1, or PDL1) from the immunosuppressive microenvironment where the tumor locates while several checkpoint inhibitors have been approved for clinical application." (PMID 37197436, 2023). "Utilizing ICIs to block inhibitory PD-1/PD-L1 and CTLA-4/CD80/86 signaling pathways improves the generation of efficient immune responses against cancer cells, revitalizes tumor antigen recognition, and ultimately leads to tumor death." (PMID 37038154, 2023). "Furthermore, CD200R is reportedly overexpressed and co-expressed with multiple immune checkpoints, including PD-1, CTLA-4, and TIM-3, in tumor-infiltrating T cells in NSCLC tumor tissues." (PMID 37894750, 2023). "Moreover, risk scores were negatively related to the expression of CD274, CTLA4, ICOS, LAG3, PDCD1, and PDCD1LG2 and negatively correlated with CD8+, CD4+, and Treg tumor-infiltrating immune cells." (PMID 37674251, 2023).
tumor (continued). "There was uniform absence of CTLA4 expression in both lymphocytes and tumor cells of R and C, with a mean of <1% staining seen in involved nodes of C." (PMID 36751105, 2023). "Targeting immune inhibitory antigens such as PD-1, PD-L1 and CTLA-4 with either nivolumab, pembrolizumab or ipilimumab have been tested in clinical studies focused on GBM, showing promising results in terms of both safety/feasibility and anti-tumor activity." (PMID 37025994, 2023). "Activation of cytotoxic T cells relies not only on positive costimulatory signals from the T cell receptor (TCR) binding to tumor antigens, but also on negative coinhibitory signals, such as the PD-1/PD-L1 axis and CTLA-4/B7 axis." (PMID 37926852, 2023). "A greater relevance of CTLA4 and/or Tregs than PD1/PD-L1 as immunosuppressive mechanisms at initial tumor stages may explain the superior sensitivity to anti-CTLA4 in this model." (PMID 37928272, 2023). "Specifically, they are antibodies targeted against established and emerging immune checkpoints, such as cytotoxic T-cell antigen 4 (CTLA4), programmed cell death ligand 1 (PD-L1) and programmed cell death 1 protein (PD-1) on CD8-positive T cells, which promote the destruction of tumor cells." (PMID 36765649, 2023). "We used TISIDB database to predict and analyze the correlation between CHSY1 expression and immune factors including PD-L1, PD1, LAG3, IDO1 and CTLA4, so that we could observe the interaction between CHSY1 and the CRC tumor microenvironment." (PMID 37749638, 2023). "A recent study suggested that tumor vessel perfusion could be used to predict the responsiveness of anti-PD1 and anti-CTLA4 therapy." (PMID 36969495, 2023). "Anti-CTLA-4 antibodies with reduced ADCC function (IgG2, tremelimumab) have decreased activity, whereas afucosylated Fc domains with increased ADCC demonstrate enhanced anti-tumor activity." (PMID 37753969, 2023). "Anti-CTLA-4 antibodies enhance immune responses and suppress neoantigen expression by activating the binding of CD28 to B7 and that of T cell receptor to major histocompatibility complex molecules, resulting in tumor cell elimination." (PMID 37305530, 2023). "Using paired tumor biopsies, we found that tumor-infiltrating immune cells had a reduced expression of inhibitory immune checkpoints (VISTA, PD-1, PD-L2) and an elevated expression of T-cell activation markers (CTLA-4, OX40L) after elraglusib treatment." (PMID 37446056, 2023). "Taken together, our results suggested that upregulation of CD40, CTLA4, ARG1, STAT3, IDO, and CD274, which were included in tumor inflammation signature, in the TME of KRASmut, could be characteristic of immune suppression." (PMID 36831441, 2023). "For example, CTLA-4 expressed on tumor-infiltrating Treg cells (TI-Tregs) can bind to CD80/86 with higher affinity than CD28, impairing the maturation of APCs and costimulatory signals to further hinder the activation of anti-tumor CD4+ and CD8+ T cells." (PMID 39872303, 2023). "Moreover, the blockade of several immune checkpoints, such as PD-1, CTLA-4, and LAG-3, represents an alternative way of inducing anti-tumor immunity." (PMID 37064017, 2023). "Thus, we randomized mice bearing either a poorly responsive small (~ 100 mm3) B78 tumor or two large (~ 350 mm3 per tumor) A20 tumors into 4 treatment groups: PBS, anti-CTLA-4, CpG + OX40, and CpG + OX40 + anti-CTLA-4." (PMID 37016127, 2023). "CTLA-4 is another popular inhibitory immune checkpoint that could competitively bind CD80 and CD86 against CD28, interrupting the activation of anti-tumor immunity." (PMID 37305457, 2023). "Moreover, in the tumor resection mice model, the multi-agent-loaded hydrogel showed significantly higher efficacy in inhibiting tumor reoccurrence, compared with the DOX/anti-CTLA-4/anti-PD-1 mixed solution." (PMID 37265604, 2023).
tumor (continued). "Furthermore, CTLA4 and LAG3 were negatively expressed in tumor-infiltrating lymphocytes, while CD96 and HAVCR2 were highly expressed in cluster CD8_1, indicating functional exhaustion of cells in this cluster within TME." (PMID 37533434, 2023). "For instance, Treg cells are thought to be suppressors of overactive immunological responses by producing CTLA4, IL-10, and TGF, which may allow tumor cells to evade the immune system." (PMID 37860186, 2023). "Furthermore, tumor-induced acidosis stimulates TAM production and increases CTLA-4 expression on T cells." (PMID 36900322, 2023). "Meanwhile, the addition of PD-1 or PD-L1 blockers allows the restoration of the anti-tumor activity of radiation-induced exhausted CD8+ T cells, and the addition of CTLA-4 blockers serves to overcome the RT-induced inhibitory signals on APCs and regulatory T cells." (PMID 38069095, 2023). "In the case of delivery of anti-CTLA4 to tbLN, it is likely that the tumor tissue outcompetes the non-diseased tissue in terms of ICI availability, thereby minimizing unwarranted off-target effects." (PMID 37259163, 2023). "Compared to untreated mice, tumor burden in mice treated with OT-I T-cell were significantly smaller, which was further enhanced by CTLA4 but not PDL1 blocking antibodies." (PMID 37258521, 2023). "In liver metastases, the immunosuppressive checkpoints CTLA-4, LAG-3, B7-H3, and ARG1were highly expressed within the outer invasive margin and distal region, but their levels were lower or similar inside the tumors compared with other metastatic tumor sites." (PMID 37768208, 2023). "Additionally, a strong correlation between RHBDF2 upregulation and immune checkpoint genes (PDCD1, CD274, LAG3, CTLA4, TIGIT, HAVCR2) was observed in HCC, and these immune checkpoint genes can contribute to tumor immune escape and promote tumor progression." (PMID 36943228, 2023). "tumor cells could escape immunosurveillance via interacting with immune modulator markers, such as TNFSF9, CTLA4 and PDCD1, which are known as important molecules for cancerigenesis or cancer immunotherapy." (PMID 37013511, 2023). "This is reflected in the sum est freq of tumor specific TILs in the anti-CTLA-4 group in which the sum est freq is increased in all CTLA-4 inhibited samples, although it is not statistically significant (P value = 0.2969)." (PMID 37359554, 2023). "For example, polyethylene glycol-chitosan-alginate NPs carrying anti-CTLA-4 siRNA could concomitantly block A2AR and CTLA-4 and facilitated CD8+ T-mediated tumor eradication in TME." (PMID 37273004, 2023). "IFN-γ can induce the expression of more than 200 genes, including those involved in immune evasion by tumor cells, such as PD-L1, PD-L2, CTLA-4, CIITA, non-classical MHC class Ib antigens, IDO1, and CXCL12." (PMID 37444608, 2023). "Simultaneously blocking other immune checkpoint molecules, such as CTLA-4, PD-1, and Tim-3, in addition to CD200 may synergistically boost anti-tumor activity." (PMID 36756156, 2023). "Similarly, single-cell RNA sequencing on tissues derived from patients with dCCA also revealed that tumor infiltrating Tregs were abundant in dCCA tumors with immunosuppressive genes such as TIGIT, CTLA4, and TNFRSF18 highly expressed." (PMID 37197436, 2023). "It inhibits the binding of CTLA-4 with CD80/CD86, blocks the CTLA-4 pathway, restores the second signal of T cells, increases the number of active effector T cells, and thus enhances the immune attack on tumor cells." (PMID 37860188, 2023). "Interestingly, the tumor cells in two TNBC groups displayed different expression patterns of the critical immunotherapeutic targets, such as PD-1/L1, CTLA4, CD47, CDK4/6, PARP1/2 and DDR1/2." (PMID 36998014, 2023). "CTLA-4 is responsible for delivering inhibitory signals to T cells so that they do not kill other cells, including tumor cells." (PMID 36604694, 2023).